PDE4B (phosphodiesterase 4B)
Diseases named in the same sentence as PDE4B in open-access papers (continued):
Sharing a sentence is not in itself a finding about the gene and the disease.
tumor (20 papers, 2012 to 2025). "Subclone 11 contained EIF4G3, IL12RB2, and PDE4B mutations, and all three mutations had zero allele frequencies in the tumor sample P6_T11, indicating the possibility of secondary driver genes for this subclone." (PMID 34075047, 2021). "In addition, PDE4B protein level was significantly associated with tumor grade (p = 0.036) and T stage (p = 0.003)." (PMID 34977026, 2021). "PDE4B has been shown to contribute to a pro-inflammatory environment within tumors, which can support tumor growth and immune evasion." (PMID 39202484, 2024). "Phosphodiesterase 4B (PDE4B) was reported as regulated by BHLHE40 which was a direct regulator of the pro-tumor gene and played a key role in the polarization of neutrophils in PDAC18." (PMID 38769374, 2024). "Excitingly, there was a co-localized expression of PDE4B and CD8 in tumor tissues, and PDE4B and CD8 expressions were positively correlated." (PMID 39132169, 2024). "Analysis of all relevant literature on PDE4B so far revealed that the expression of PDE4B was upregulated in the majority of tumor tissues." (PMID 36278172, 2022). "Secondary resistant tumor BoC10 showed a strong upregulation of two family members of cAMP-specific phosphodiesterases (PDE4B and PDE4D) of 206 and 15-fold, respectively, compared to the 5-day controls." (PMID 34271981, 2021). "Since our finding also revealed its tumor promoting role of PDE4B and inhibition of its activity can reverse its oncogenic function." (PMID 34977026, 2021). "Accordingly, we compared the level of the Pde4b transcript in the normal colonic epithelium from tumor-free colons with that from tumor-bearing colons." (PMID 30188895, 2018). "Gross tumor numbers were measured in the colons of ApcMin/+ mice from the series of backcross-intercross generations, carrying the Pde4b+/+, Pde4b+/- and Pde4b-/- genotypes." (PMID 30188895, 2018). "In contrast, TAM (tumor‐associated macrophage) C16 was enriched in lung tumors and highly expressed PDE4B but not IL1B, MDM2, or PELI1." (PMID 38010945, 2024). "Altogether, we concluded that pharmacological repression of PDE4B by rolipram could partly rescue the tumor-promoting effects induced by PDE4B overexpression." (PMID 34977026, 2021). "Our data consistently revealed that inhibition of PDE4B by rolipram could rescue the tumor-promoting effects from PDE4B overexpression on cell invasion and EMT, suggesting that rolipram would be a promising UBC pharmacological inhibitor targeting PDE4B." (PMID 34977026, 2021). "Pde4b+/+ animals show the lowest average colon tumor count 2.4 +/- 2.2." (PMID 30188895, 2018). "Pde4b+/- animals show higher average colon tumor counts than Pde4b+/+ animals 3.3 ± 2.9." (PMID 30188895, 2018). "Thus, we explored whether pharmacological inhibition of PDE4B by rolipram could rescue the tumor-promoting effects induced by PDE4B overexpression." (PMID 34977026, 2021). "Mechanistically, PDE4B enhances hypoxia-induced VEGF production by catalyzing cAMP hydrolysis, which regulates the tumor microenvironment and promotes angiogenesis." (PMID 40129976, 2025). "In conclusion, our results emphasize the potential clinical utility of PDE4B, PDE4D, and SFRP5, genes that impact tumor initiation, progression, and metastasis, as biomarkers for CRC." (PMID 39202484, 2024). "Gene expression of all three studied genes, PDE4B (p < 0.0001), PDE4D (p < 0.0001), and SFRP5 (p < 0.0001), was significantly lower in tumor tissue in comparison to the control tissue." (PMID 39202484, 2024). "Mechanistically, FTO inhibits phosphodiesterases 4B (PDE4B) and 1C (PDE1C) via demethylase activity via m6A modification, resulting in cAMP accumulation and reduced stemness in OC and tumor initiation." (PMID 38544837, 2024).
tumor (continued). "This highlights DPY30 as a critical regulator of epigenetic modifications supporting GSC-driven tumor progression and identifies both DPY30 and PDE4B, a downstream target of DPY30, as potential therapeutic targets in GBM, with the PDE4 inhibitor rolipram as a promising agent." (PMID 40565099, 2025). "Furthermore, miR-361 also suppressed the expression of multiple prometastatic genes and tumor microenvironment-related genes, including MEF2D, ROCK1, WNT7A, VEGF-A, PDE4B, and KPNA4." (PMID 31287002, 2019). "However, the action of PDE4B have never been reported in tumor, the exploration of PDE4B is innovative." (PMID 39132169, 2024).
neurological disorders (5 papers, 2016 to 2023). "Currently, promising treatments are being developed for neurological diseases that against PDE4B and PDE4D." (PMID 34977026, 2021).
neurodevelopmental disorder (3 papers, 2017 to 2025). A behavioral and cognitive disorder with onset during the developmental period that involves impaired or aberrant development of intellectual, motor, or social functions. "The strongest SNP associations were near genes previously identified for neuronal development and neurodevelopmental disorders, including PAPPA2 (rs147036913), SEMA6D (rs35175834), PDE4B (rs10789205), and CSMD1 (rs7830752)." (PMID 40490728, 2025).
infection (2 papers, 2019 to 2026). The state of being infected such as from the introduction of a foreign agent such as serum, vaccine, antigenic substance or organism. "In contrast, PDE4B activation reduces fungal burden in the brain, including when administered after infection onset." (PMID 41805786, 2026).
adenocarcinoma (1 paper, 2020). A common cancer characterized by the presence of malignant glandular cells. "Furthermore, long term inhibition of PDE4 by NCS 613 leads to induction of PDE4B 96 kDa in adenocarcinoma A549 cell line." (PMID 32973507, 2020).
cardiovascular disease (1 paper, 2024). "This included theophylline and its derivatives (dyphylline and enprofylline), selective PDE4B inhibitors (cilomilast and roflumilast), and other drugs indicated for cardiovascular disease (amrinone and trapidil) or patients with COPD (roflumilast and cilomilast)." (PMID 39408698, 2024).
immune dysfunction (1 paper, 2025). "Studies from Chinese researchers utilizing single-cell sequencing and genome-wide association analyses have revealed that cAMP signaling deficiency leads to immune dysfunction, and that PDE4B inhibition by dipyridamole demonstrates therapeutic potential in animal models." (PMID 41312366, 2025).
kidney disease (1 paper, 2025). "Cpd-6c, a rutaecarpine derivative that targets PDE4B, is an important regulator driving irritation in cisplatin-induced kidney disease and has been reported to alleviate AKI." (PMID 40351427, 2025).
neurodegenerative disease (1 paper, 2023). A disorder of the central nervous system characterized by gradual and progressive loss of neural tissue and neurologic function. "Additionally, molecular docking studies with human phosphodiesterase 4B, AChE, and BuChE also support the proposal that the top candidate compounds could benefit future neurodegenerative disease treatment." (PMID 37894669, 2023).
PDE4B also shares sentences with these, for which no sentence is quoted: hematological malignancies (3 papers); non-small cell lung carcinoma (3); atopic dermatitis (2); gastritis (2); abdominal aortic aneurysm (1); alcohol (1); alcoholic liver diseases (1); allergies (1); aneurysm (1); atherosclerosis (1); atopic asthma (1); B-cell lymphoblastic leukemia (1); brain diseases (1); cerebellar ataxia (1); childhood asthma (1); colon (1); cystic fibrosis (1); diabetic retinopathy (1); discoid lupus erythematosus (1); duodenitis (1); Ebola virus disease (1); endometriosis (1); experimental autoimmune encephalomyelitis (1); gestational diabetes (1); glaucoma (1); hearing loss (1); Huntington disease (1); Hyperglycemia (1); Hyperinsulinemia (1); hypothyroidism (1).
A further 17 diseases each share a sentence with PDE4B in 1 paper.